FAM157B (family with sequence similarity 157 member B)
Gene: Transcribed unprocessed pseudogene on chromosome 9 (138,243,620 to 138,253,217, forward strand). Ensembl gene ENSG00000233013.
Diseases named in the same sentence as FAM157B in open-access papers:
FAM157B is named in the same sentence as 1 disease in open-access papers, as found by Europe PMC text mining. Sharing a sentence is not in itself a finding about the gene and the disease.
FAM157B shares sentences with these, for which no sentence is quoted: lung adenocarcinoma (1 paper).